NRF1 (nuclear respiratory factor 1)
Diseases named in the same sentence as NRF1 in open-access papers (continued):
Sharing a sentence is not in itself a finding about the gene and the disease.
breast tumor (2 papers, 2018 to 2020). "We detected increas(ed levels of NRF1 protein in breast tumor tissues (both benign and malignant) compared to control tissues (normal breast tissues)." (PMID 30486409, 2018). "Taken together, these findings provide evidence in support of elevated NRF1 protein levels in human breast tumors." (PMID 30486409, 2018). "Similarly, our previous meta-study showed that NRF1 gene expression significantly increases with the progression of breast tumor grades." (PMID 30486409, 2018). "In ER-/HER2 + breast tumors, WNT7B was shown to be a direct transcriptional target of the androgen receptor (AR) and predicted to be regulated by Nuclear respiratory factor 1 (NRF1)." (PMID 33625717, 2020).
Cachexia (2 papers, 2024 to 2025). Severe weight loss, wasting of muscle, loss of appetite, and general debility related to a chronic disease. "Interestingly, the downregulated genes in muscle ECs of B16F10-cachexia mice were enriched for multiple cofactors of the transcriptional coactivator peroxisome proliferator-activated receptor (PPAR)γ coactivator 1α (PGC1α), such as Nrf1, PPARδ, Mef2, Hnf4 and forkhead box O1 (FOXO1)." (PMID 40419762, 2025).
cervical cancer (2 papers, 2020). A primary or metastatic malignant neoplasm involving the cervix. "Western blot analysis showed that the expression of TBP, rather than NRF1, in cervical cancer cells was significantly greater than that in ECT1/E6E7 cells." (PMID 32444598, 2020).
Chagas disease (2 papers, 2012 to 2016). A parasitic infection caused by Trypanosoma cruzi. "We found that mtDNA was oxidized and unfit to carry out mtDNA replication in infected cardiomyocytes, and these defects were not related to PGC-1α, but were associated with nonresponsiveness of the NRF1/2 pathway of antioxidant gene expression in Chagas disease." (PMID 23316324, 2012). "The decline in SIRT1/PGC1α activity was not the key mechanism in mitochondrial biogenic defects in Chagas disease, and therefore SIRT1-targeted therapy did not normalize the PGC1α/NRF1-dependent mitochondrial biogenesis and cardiac remodeling in chagasic disease." (PMID 27764247, 2016).
chronic obstructive pulmonary disease (2 papers, 2022 to 2025). A chronic and progressive lung disorder characterized by the loss of elasticity of the bronchial tree and the air sacs, destruction of the air sacs wall, thickening of the bronchial wall, and mucous accumulation in the bronchial tree. "Furthermore, in a rat model of chronic obstructive pulmonary disease, testosterone supplementation has been shown to inhibit the activation of NRF1 and p65 in lung epithelial cells, thereby reducing pulmonary inflammatory responses." (PMID 40872527, 2025). "Moreover, in chronic obstructive pulmonary disease, NRF1 was found to mediate inflammatory injury through the regulation of the NF-κB signaling pathway in pulmonary epithelial cells." (PMID 35704676, 2022). "Besides, our previous studies showed that NRF1 transcriptionally activates the p65 subunit of nuclear factor kappa B (NF-κB), thus up-regulating the NF-κB signaling in chronic obstructive pulmonary disease." (PMID 35704676, 2022).
cognitive deficits (2 papers, 2021 to 2023). "Besides preventing cognitive impairment and neurodegeneration through its antioxidant and anti-inflammatory properties, resveratrol has been shown to be able to enhance mitochondria biogenesis by acting on its main effectors, including PGC-1α, SIRT1, AMPK, ERRs, TERT, TFAM, NRF-1 and NRF-2." (PMID 36237161, 2023).
gastric cancer (2 papers, 2024). A primary or metastatic malignant neoplasm involving the stomach. "In that study, it was determined that ABH1-mediated demethylation of m6A in gastric cancer cells selectively affects transcriptional activity of NRF1, thereby attenuating the launch of AMP-activated protein kinase (AMPK) signaling and promoting the Warburg phenotype in gastric cancer cells." (PMID 39329974, 2024).
head and neck squamous cell carcinoma (2 papers, 2015 to 2022). A squamous cell carcinoma that arises from any of the following anatomic sites: lip and oral cavity, nasal cavity, paranasal sinuses, pharynx, larynx, and salivary glands. "Furthermore, we used The Cancer Genome Atlas (TCGA) database to examine the overall survival rate of head and neck squamous cell carcinoma due to different expression levels of NRF1." (PMID 26201446, 2015).
homocysteinemia (2 papers, 2021 to 2024). "In rodent models, homocysteinemia can disrupt the mitochondrial function by reducing the levels of myotonic dystrophy protein, mitochondrial transcription factor A (mtTFA), and its regulator nuclear respiratory factor 1 (NRF-1)." (PMID 38921477, 2024). "In addition, low levels of (mRNA) Nrf1 have been observed in Cystathionine β synthase (CBS) heterozygous-null mice modeling hyperhomocysteinemia, a syndrome characterized by skeletal muscle weakness and fatigability." (PMID 34359231, 2021).
Hyperkeratosis (2 papers, 2012 to 2013). Hyperkeratosis is a histopathological term defining a thickened stratum corneum and may be present in many different skin conditions, with many possible overlaps. "Our previous studies demonstrated that the NRF2 and NRF1 signaling pathways can be activated by iAs3+ in human HaCaT cells, suggesting that NRF2 and NRF1 may be involved in the pathogenesis of arsenic-induced skin cancer and hyperkeratosis." (PMID 23710286, 2013).
Hypertension (2 papers, 2021 to 2022). The presence of chronic increased pressure in the systemic arterial system. "This study provides insights into the central mechanism underlying the mediating role of Nrf1 in the development of hypertension, implicating that the Nrf1 may represent a potential target for prevention and treatment of hypertension." (PMID 34938159, 2021). "However, the brain mechanisms underlying PVN Nrf1 modulating sympathoexcitation and blood pressure during the development of hypertension remains unclear." (PMID 34938159, 2021). "Compared with sham controls, the expression of Nrf1 in the 2K1C group was found to be increased, and this might be mediated via the oxidative stress response in the PVN during hypertension, that is, the responsiveness of Nrf1 increases during hypertension." (PMID 34938159, 2021). "Administration of shNrf1 knocked down the expression of Nrf1 and reduced the expression of excitatory neurotransmitters, increased the expression of inhibitory neurotransmitters, and reduced the production of reactive oxygen species (ROS), and attenuated sympathoexcitation and hypertension." (PMID 34938159, 2021). "In this study, an adeno-associated virus (AAV) vector carrying the shRNA targeting rat Nrf1 gene (shNrf1) was injected into bilateral PVN of male rats underwent two kidneys and one clip to explore the role of Nrf1 in mediating the development of hypertension and sympathoexcitation." (PMID 34938159, 2021). "In this experiment, shNrf1 AAV vector was given to bilateral PVN of male rats underwent two kidneys and one clip to explore whether knocking down Nrf1 affects ROS content, neurotransmitter expression, and NMDAR subunits, thereby affecting the development of hypertension." (PMID 34938159, 2021). "Nrf1 has been reported to modulate the transcription of several genes related to antioxidant expression such as SOD1 and cytochrome c oxidase subunits, and thus may be involved in ROS regulation during the pathophysiology of hypertension." (PMID 34938159, 2021).
injury (2 papers, 2016 to 2024). Damage inflicted on the body as the direct or indirect result of an external force, with or without disruption of structural continuity. "Both endogenous and exogenous induction of Nrf1 activation have been shown to effectively protect against nerve injury." (PMID 39198723, 2024). "Studies have suggested that NRF1 and NRF2 promote mitochondrial biogenesis as well as play crucial role in neuronal survival after acute brain injury." (PMID 26784894, 2016).
leukemia (2 papers, 2020 to 2023). A malignant (clonal) hematologic disorder, involving hematopoietic stem cells and characterized by the presence of primitive or atypical myeloid or lymphoid cells in the bone marrow and the blood. "In leukemia, well-known oncogenes (such as MYC and NRF1) were among the top edge gainers, while the well-known tumor suppressor IKZF1 is the most significant edge loser." (PMID 32728046, 2020).
lipid metabolic disorder (2 papers, 2018 to 2019). "In addition to lipid metabolic disorders resulting from loss of Nrf1’s function to regulate LPIN1, PGC-1β and other metabolic genes, NASH has a not-yet-identified characteristic of refractory inflammation." (PMID 30562963, 2018).
liver disease (2 papers, 2023 to 2024). "As Nrf1 deficiency for ~7 days to ~7 weeks corresponded with signature features of liver disease progression and this was distinct from Nrf2, we next examined their roles in protecting against MASH progression to liver tumorigenesis." (PMID 39125617, 2024). "Using novel approaches, we elucidated the potential of miR-122 in modulating key transcription factors such as NRF1 and E2F4, which are intrinsically linked to liver disease." (PMID 37627157, 2023). "Firstly, through transcriptome analysis of polyribosome-bound RNAs, we discovered that miR-122 exhibits potential antagonistic effects on specific transcription factors known to be dysregulated in liver disease, including nuclear respiratory factor-1 (NRF1) and the E2F transcription factor 4 (E2F4)." (PMID 37627157, 2023). "Thus, enhancing Nrf1 and/or Nrf2 activity in the liver may be important for mitigating MASH and preventing liver disease progression." (PMID 39125617, 2024).
liver fibrosis (2 papers, 2024 to 2026). "Our findings demonstrate that macrophage Nrf1 deficiency mediates liver fibrosis by impairing mitochondrial biogenesis and respiratory function." (PMID 41424862, 2026). "Initially, the expression of macrophage Nrf1 was analyzed in multiple mouse models as well as liver fibrosis patient samples." (PMID 41424862, 2026). "Together, these findings strongly support the macrophage-specific nature of Nrf1 in the inflammatory response of macrophages in liver fibrosis progression." (PMID 41424862, 2026). "Herein, this study was conducted to elucidate the roles of macrophage Nrf1 in regulating liver fibrosis." (PMID 41424862, 2026). "Herein, this translational study was designed to gain mechanistic insights into the role of macrophage Nrf1 in the progression of liver fibrosis." (PMID 41424862, 2026). "In summary, our study elucidates the functional roles of macrophage Nrf1-Foxo1 signaling in the pathogenesis of liver fibrosis." (PMID 41424862, 2026). "To elucidate the role of macrophage-specific Nrf1 in liver fibrosis more precisely, we utilized the Cre-LoxP system to generate mice with myeloid-specific knockout of Nrf1 (Nrf1M-KO)." (PMID 41424862, 2026). "Subsequently, myeloid-specific Nrf1-knockout (Nrf1M-KO) mice were generated to study the contribution of macrophage Nrf1 in three kinds of mouse liver fibrosis models." (PMID 41424862, 2026). "Our results underscore the critical role of Nrf1 in regulating mitochondrial activity and inflammatory responses in macrophages during the progression of liver fibrosis." (PMID 41424862, 2026). "Here, we investigated protective effects of hepatocyte Nrf1 and Nrf2 against MASH-linked liver fibrosis and tumorigenesis." (PMID 39125617, 2024). "Figuring out the precise mechanism of macrophage Nrf1 in liver fibrosis could provide valuable insights, potentially aiding in halting and effectively reversing ongoing liver fibrosis." (PMID 41424862, 2026). "Thus, further investigation is necessary to elucidate the mechanisms through which Nrf1 regulates cellular energy metabolism in liver fibrosis progression." (PMID 41424862, 2026). "Additionally, the exacerbation of liver fibrosis, inflammation, and mitochondrial dysfunction occurs specifically upon deletion of Nrf1 in myeloid cells, including Kupffer cells and bone marrow-derived macrophages." (PMID 41424862, 2026). "Our second objective was to examine the effect of inducing hepatic Nrf1, Nrf2, or both on alleviating liver fibrosis in mice fed an HFFC diet for 24 weeks while also being exposed to the liver fibrosis-inducing agent, carbon tetrachloride, for the first 15 weeks." (PMID 39125617, 2024). "But to our knowledge, our previous study has been the only one to systematically investigate the combined roles of hepatic Nrf1 and Nrf2 on stress defenses counteracting MASH, and this study is the only one to assess the combined roles of hepatic Nrf1 and Nrf2 on MASH-linked liver fibrosis and HCC." (PMID 39125617, 2024). "However, the immune- regulatory mechanism specific to macrophage Nrf1 in regulating mitochondrial reprogramming and liver fibrosis remains unknown." (PMID 41424862, 2026). "Fluorescence co-localization of Nrf1 and CD68+ macrophages was detected in three types of liver fibrosis models." (PMID 41424862, 2026). "Collectively, these results indicate that macrophage Nrf1-Foxo1 interaction regulates its target gene KLF16, which may be involved in energy imbalance and subsequent liver fibrosis." (PMID 41424862, 2026).
myelogenous leukaemia (2 papers, 2008 to 2025).
myocardial infarction (2 papers, 2022 to 2025). Gross necrosis of the myocardium, as a result of interruption of the blood supply to the area, as in coronary thrombosis. "But, following myocardial infarction (MI), Nrf1-cKO hearts showed decreased cardiac function (measured as fractional shortening, ejection fraction, and myocardial wall motion), but with increased fibrotic scarring." (PMID 40703332, 2025).
myocardial ischemia (2 papers, 2020 to 2021). A disorder of cardiac function caused by insufficient blood flow to the muscle tissue of the heart. "We found that QSG could promote the mitochondrial function and antioxidant response via the PGC-1α/NRF1/TFAM pathway to alleviate the effects of myocardial ischemia on mitochondrial dysfunction and oxidative stress in myocardial cells." (PMID 35003305, 2021).
nasopharyngeal carcinoma (2 papers, 2015 to 2021). A carcinoma arising from the nasopharyngeal epithelium. "In an in vitro model of nasopharyngeal carcinoma, radioresistance was associated with upregulated expression of miR-504, leading to lower levels of NRF1." (PMID 33069104, 2021). "Serum from nasopharyngeal carcinoma patients showed that miR-504 was up-regulated during different weeks of radiotherapy and correlated with tumour volume, lymph nodes, and metastasis stages, demonstrating that miR-504 regulated radioresistance by down-regulating the expression of NRF1." (PMID 33069104, 2021).
neuropathy (2 papers, 2012 to 2024). A disorder affecting the nervous system that manifests with pain, tingling, numbness, and/or muscle weakness. "Specific genes increased in patients withoutlinezolid-associated neuropathy included ATG4C, BAX, and IGF1, while patients onlinezolid who suffered from neuropathy had an increase in AURKB, CASP3, CASP8, CDK1,CDKN1B, CEBPB, NADSYN1, NRF1, GPX7, and SBSN." (PMID 38939039, 2024).
pulmonary fibrosis (2 papers, 2020 to 2023). Chronic progressive interstitial lung disorder characterized by the replacement of the lung tissue by connective tissue, leading to progressive dyspnea, respiratory failure, or right heart failure. "We hypothesize that targeting Nrf1/Tcf11, the major regulator of proteasome subunits expression, might constitute a promising therapeutic approach in pulmonary fibrosis by interplaying between the UPS, MMPs, and the Wnt/B-catenin pathway." (PMID 32485920, 2020).
renal cell carcinoma (2 papers, 2024 to 2025). "In addition, NRF-1 activity has also been associated with estrogen-induced breast carcinogenesis, and renal cell carcinoma where it regulates the expression of the TFE3 gene required for cellular energy metabolism during proliferation." (PMID 39742254, 2024). "In 769-P renal cell carcinoma cells, overexpression of FTO leads to the upregulation of PGC1A, TFAM, and NRF1 genes, which are involved in mitochondrial biogenesis." (PMID 40361322, 2025).
triple-negative breast carcinoma (2 papers, 2022 to 2025). An invasive breast carcinoma which is negative for expression of estrogen receptor (ER), progesterone receptor (PR), and human epidermal growth factor receptor 2 (HER2). "The putative promotion of triple-negative breast cancer was viewed to arise by Nrf1-mediating proteasomal cytoprotective response to resist against the proteasomal inhibitor treatments 485 and/or Nrf1-driving enhanced expression of programmed death ligand 1 (PD-L1) for its immune evasion." (PMID 40703332, 2025).
viral infection (2 papers, 2019 to 2021). "The aberrant expression of certain components in the RC complexes and antioxidant enzymes as well as the NRF1/2/TFAM signaling correlated well with a previous report that virus infection stimulates excessive ROS production and mitochondrial dysfunction." (PMID 31011285, 2019). "While the expression levels of TFAM, an executor of the canonical PGC-1α pathway, were consistently increased from 2 to 16 h after infection, suggesting that virus infection promotes TFAM expression with an unknown mechanism that is independent on either NRF1 or NRF2." (PMID 31011285, 2019). "Interestingly, the virus infection at the late stage (at 16 h after infection) stimulated TFAM expression but decreased the levels of both NRF1 and NRF2, indicating that virus infection activated TFAM signaling independent of either NRF1 or NRF2." (PMID 31011285, 2019).
vitamin D deficiency (2 papers, 2022 to 2023). A nutritional condition produced by a deficiency of VITAMIN D in the diet, insufficient production of vitamin D in the skin, inadequate absorption of vitamin D from the diet, or abnormal conversion of vitamin D to its bioactive metabolites. "Consistent with the rat data, vitamin D deficiency significantly reduced NRF1 gene expression in mice gastrocnemius muscle (−34% vs. control mice)." (PMID 36434267, 2022). "Prolonged vitamin D deficiency reduces muscle health by decreasing mtDNA content and the expression of critical biogenesis-related factors (for example, PGC-1α, NRF1, NRF2, PPARα, and COXIV)." (PMID 38004107, 2023).
acute kidney injury (1 paper, 2025). Sudden and sustained deterioration of the kidney function characterized by decreased glomerular filtration rate, increased serum creatinine or oliguria. "Acute kidney injury caused by IRI is one of the most common complications in cardiac surgery, and myeloid deficiency of NRF1 led to elevated inflammatory responses and tissue damage after IRI-AKI surgery." (PMID 40374603, 2025).
acute liver failure (1 paper, 2018). Rapid deterioration of liver function causing encephalopathy and coagulopathy. "During acute liver failure induced by LPS/D-GalN, CO induced the levels of mitochondrial PINK1 and Parkin, and PGC1α-mediated NRF1 and TFAM gene expressions, which could lead to promotion of mitochondrial turnover and biogenesis." (PMID 30333475, 2018).
acute lymphoblastic leukemia (1 paper, 2021). Leukemia with an acute onset, characterized by the presence of lymphoblasts in the bone marrow and the peripheral blood. "Inhibition of NGLY protein inhibition inactivates NRF1 and potentiates proteasome inhibitor cytotoxicity in MM and T-ALL (acute lymphoblastic leukemia) cell lines." (PMID 33799793, 2021).
acute myeloid leukemia (1 paper, 2020). Acute myeloid leukemia (AML) is a group of neoplasms arising from precursor cells committed to the myeloid cell-line differentiation. "Indeed, Nrf1, DDI2, and NGLY1 exhibit a correlated essentiality for cell survival in several acute myeloid leukemia (AML) cell lines." (PMID 32456207, 2020).